IL2 (interleukin 2)
Diseases named in the same sentence as IL2 in open-access papers (continued):
Sharing a sentence is not in itself a finding about the gene and the disease.
Bovine Tuberculosis (4 papers, 2011 to 2023). "Therefore, some flow methods based on intracellular IFN-γ and IL-2 detection have been established in the diagnosis of bovine tuberculosis, which are helpful for early detection and timely control of the disease to reduce the loss." (PMID 37376677, 2023). "For instance, calves typically infected with bovine tuberculosis had a predominance of TNF-α+IFN-γ+IL-2+ and TNF-α+IFN-γ+IL-2− CD4+ T cells with a TEM phenotype." (PMID 36960295, 2023).
brain infarct (4 papers, 2021 to 2025). "In this study, we found that IL-6 and IL-2 were elevated in aSAH patients who presented with new cerebral infarcts on CT imaging at 1 week or 2 weeks post-injury when compared to patients who did not demonstrate this finding." (PMID 40427506, 2025). "For example, naïve Treg transfer or Treg upregulation by IL-2/IL-2 antibody complexes have been reported to alleviate symptoms of cerebral infarction models." (PMID 35911740, 2022). "Using a mouse cerebral infarction model, we showed that brain Tregs are activated and proliferate in both cervical lymph nodes and in the brain through the action of IL-2, IL-33, and serotonin." (PMID 35911740, 2022). "Thus, this study shines light onto IL-6 and IL-2 as potential targets contributing to the pathophysiology of aSAH complicated with cerebral infarct." (PMID 40427506, 2025).
brain injury (4 papers, 2018 to 2021). Acute and chronic (see also brain INJURIES, CHRONIC) injuries to the brain, including the cerebral hemispheres, CEREBELLUM, and brain STEM. "Administration of IL-2C prolongs the half-life of IL-2 and leads to upregulation of Treg cells in the ipsilateral brain cortex 3 days after traumatic brain injury." (PMID 34073791, 2021). "Pretreatment involving IL-2/IL-2R can potentially decrease the severity of an ischemic brain injury." (PMID 33830475, 2021).
Burkitt lymphoma (4 papers, 2017 to 2024). A rare form of malignant mature B-cell non-Hodgkin lymphoma. "PHA-stimulated lymphocytes produce IL-2 in two molecular sizes of 16 and 17 kDa, while Burkitt’s lymphoma cell line Daudi, produces IL-2 of 14 kDa." (PMID 39447666, 2024).
cervical tumor (4 papers, 2011 to 2024). "We have previously reported that the treatment of cervical tumour cells with low doses of IL-2 (10 IU/mL) induces increased proliferation." (PMID 39766250, 2024). "For this reason, this work aims to analyse the effect of treating cervical tumour cells with IL-2 and their response to death-inducing stimuli such as CD95." (PMID 39766250, 2024). "In conclusion, cervical tumour cells can use the IL-2 and CD95 pathways to induce their proliferation and potentially activate cytoprotective mechanisms for survival." (PMID 39766250, 2024). "For example, there are reports that cervical tumor cells express the IL-2 and erythropoietin receptors and are capable of secreting IL-2 and erythropoietin to stimulate autocrine growth." (PMID 33076315, 2020). "Considering that the CD95 and IL-2 pathways have differential effects on cervical tumour cells, we decided to evaluate whether simultaneous treatments affected the proliferation and induction of cell death." (PMID 39766250, 2024). "Thus, our results suggest that IL-2 can affect the proliferation of cervical tumour cells in a similar way that it regulates the immune cells." (PMID 31662754, 2019). "In this context, our results show the presence of the different subunits of the IL-2 receptor (IL-2Rα, IL-2Rβ, and IL-2Rγ) in HPV18+ cell lines, derived from cervical tumour tissue and the response of these tumour cells to the administration of high doses of IL-2 (100 IU/mL)." (PMID 31662754, 2019). "In this work, we observed how the cervical tumour cells HPV16 and 18 can use the IL-2 and CD95 pathways to induce their proliferation and survival." (PMID 39766250, 2024). "After determining that the treatment with high doses of IL-2 induces a decrease in the proliferation in cervical tumour cells and that this decrease does not reflect an increase in the percentage of cell death, we evaluated the phases of the cell cycle." (PMID 31662754, 2019). "However, an interesting aspect to have in mind is that we do not know the effect of stimulating the CD95 and IL-2 pathways in in vivo models with cervical tumour cells." (PMID 39766250, 2024). "The results showed that the simultaneous treatment of proliferation-inducing concentrations of anti-CD95 and IL-2 in cervical tumour cells does not have a cumulative effect, which could suggest that both stimuli could be activating the same signalling pathways." (PMID 39766250, 2024).
cholangiocarcinoma (4 papers, 2017 to 2023). A carcinoma that arises from the intrahepatic biliary tree (intrahepatic cholangiocarcinoma) or from the junction, or adjacent to the junction, of the right and left hepatic ducts (hilar cholangiocarcinoma). "Cholangiocarcinoma cell-mediated repression of T cell IL-2 expression was reversed by SPHINX31 (equivalent to pembrolizumab)." (PMID 37973660, 2023). "In addition, IL2, IL8, and interferon-gamma were found to be increased in EVs isolated from patients with cholangiocarcinoma compared with healthy controls." (PMID 37298585, 2023).
chordoma (4 papers, 2021 to 2025). Chordomas are rare malignant tumors arising from embryonic remnants of the notochord in axial skeleton. "In line with the observations in cell lines, MSigDB enrichment scores revealed that interferon alpha and gamma response, inflammatory response, and IL6/JAK/STAT3 and IL2/STAT5 signaling were among the most enriched signaling axes in chordoma but not in the pan-cancer cohort." (PMID 40901948, 2025).
chronic kidney disease (4 papers, 2018 to 2026). Impairment of the renal function secondary to chronic kidney damage persisting for three or more months. "Studies have also indicated that patients with chronic kidney disease commonly exhibit low levels of IL-2 and Treg deficiency." (PMID 41491334, 2026). "This medicament also decreases IL-2 and prevents the unwanted T-cell stimulation, as well as inhibits TGF-β1 release in patients with chronic kidney disease." (PMID 35163696, 2022).
colorectal tumor (4 papers, 2016 to 2023). "CD25+ cells enriched from peripheral blood mononuclear cells (PBMC) of colorectal tumor patients were cultured in X-VIVO15 medium, supplemented with 5% human AB serum, L-glutamine, rapamycin, interleukin-2 (IL-2), and Dynabeads human Treg expander for 21 days to expand Tregs." (PMID 33868236, 2021). "In CT26 colorectal tumor-bearing mice, a single round of PDT with porphyrin-lipid photosensitizer incorporated into a polymeric core–shell nanoparticle increased serum TNF-α, IFNγ, and IL-2 the day after PDT." (PMID 36405502, 2021).
Dry skin (4 papers, 2016 to 2025). Skin characterized by the lack of natural or normal moisture. "In uremic pruritus, it is probably secondary to CKD‐related xerosis, higher skin‐surface pH, and gut microbiota imbalance, with an immune milieu marked by elevated interleukin (IL)‐2, IL‐6, IL‐31, histamine, and altered monocyte subsets." (PMID 40528508, 2025).
fascioliasis (4 papers, 2012 to 2025). A parasitic infection that is caused by liver flukes, usually Fasciola hepatica, of sheep, goats, and cattle. "Cattle with Fascioliasis only, had significantly higher serological levels of IFN-γ, IL-1, IL-2, IL-4, and IL-18 than control and CE single infected cattle." (PMID 32915902, 2020). "In a mouse study with experimental Fasciola infection, spleen cells from BALB/c exhibited a Th2 response, producing high levels of the cytokines IL-4 and IL-5, and low levels of IFN-gamma and IL-2." (PMID 22938392, 2012). "In this study, goat monocytes showed higher levels of IL-2 and IFN-γ cytokines in response to rFg-CaBP4 protein, suggesting that these cytokines may be linked to non-protective immune responses against fascioliasis." (PMID 34022913, 2021).
glomerulonephritis (4 papers, 2010 to 2023). A renal disorder characterized by damage in the glomeruli. "Recipient age, donor age and time on dialysis were identified as independent risk variables for uncensored graft loss whereas IL-2 induction treatment, MMF treatment and glomerulonephritis as cause of ESRD were associated with improved uncensored graft survival." (PMID 28077080, 2017).
Graves disease (4 papers, 2008 to 2019). Graves' disease is an autoimmune disorder that leads to overactivity of the thyroid gland (hyperthyroidism).It is caused by an abnormal immune system response that causes the thyroid gland to produce too much thyroid hormones. "In conclusion, the expression levels and genetic polymorphisms of IL-2 and IL-10 may be potential biomarkers for the incidence of Graves’ disease in the population studied." (PMID 25667655, 2015).
Headache (4 papers, 2018 to 2026). Cephalgia, or pain sensed in various parts of the head, not confined to the area of distribution of any nerve. "Zika virus-infected subjects who reported headaches showed higher plasma levels of TNF-α, IL-17A, IL-2, IL-9, IL-12p70, MIP-1α, G-CSF, GM-CSF, and VEGF, and significantly higher levels of IL-5 (p = 0.0015) compared to those without headache." (PMID 29774022, 2018).
Hepatic steatosis (4 papers, 2013 to 2026). Steatosis is a term used to denote lipid accumulation within hepatocytes. "Conversely, induction of Treg numbers using recombinant IL2/αIL2 mAb cocktail reduced hepatic steatosis, inflammation, and fibrosis in WD-fed mice." (PMID 41597240, 2026). "Hepatic expression of IL-2 was higher in patients with biopsy-proven NASH compared to patients with hepatic steatosis in a small cohort." (PMID 40794228, 2025). "Gut immune barrier alterations in duodenal tissue samples by T lymphocytes and Th1 cytokines, and pro-inflammatory biomarkers using CD4 Alexa Fluor 488 and IL-2 PE stain, were used to establish their different patterns in liver cirrhosis or hepatic steatosis." (PMID 38473721, 2024).
Hyponatremia (4 papers, 2010 to 2023). An abnormally decreased sodium concentration in the blood. "Twenty patients (83%) with hyponatremia received three or less series of IL-2." (PMID 20145619, 2010).
idiopathic nephrotic syndrome (4 papers, 2015 to 2018). Nephrotic syndrome for which no cause has been identified. "We have previously reported that patients with idiopathic nephrotic syndrome (INS) have increased IL-2 production." (PMID 27389192, 2016). "IL-2 levels are known to become elevated during proteinuria and to normalize during remission in adults with idiopathic nephrotic syndrome and in children with Minimal change Nephrotic Syndrome (MCNS) or FSGS." (PMID 26573045, 2015). "An open-label case-control phase 1–2 pilot trial was designed to assess safety and clinical and immunologic effects of repeated administration of recombinant low dose IL2 in 5 patients with idiopathic nephrotic syndrome unresponsive to all treatments used for this condition." (PMID 26413873, 2015). "Most recently, low-dose IL-2 has also been shown to expand or modify CD4+ regulatory T cells in vitro from patients with SLE and children with the drug-resistant idiopathic nephrotic syndrome." (PMID 29619880, 2018).
immunotoxicity (4 papers, 2018 to 2023). "Moringa oleifera leaf extract alleviated the immunotoxicity of lead by lowering the plasma levels of interleukin-2 and interferon-γ." (PMID 37090774, 2023). "Together with absolute cell numbers, the cytokine production data confirmed that T cells were the main effector cells for the immunotoxicity induced by Proleukin®/IL-2." (PMID 33193321, 2020). "Correlating with these distinct outcomes, immunoliposome treatment led to significantly enhanced survival compared to untreated tumors, while soluble anti-CD137 and IL-2-Fc treatment led to reduced survival due to immunotoxicity." (PMID 29295974, 2018). "We observed increase in almost all cytokines (except IL-2, which was decreased) in response to PAC treatment, which was mitigated with the exosome formulations suggesting protection of PAC-induced immunotoxicity by exosomal formulations." (PMID 34359601, 2021). "As per clinical practice, in contrast to Proleukin®/IL-2 treatment which usually requires a longer duration of treatment to observe side effects, OKT3-mediated immunotoxicity occurs within a shorter time frame." (PMID 33193321, 2020).
infarction (4 papers, 2016 to 2022). A localised pathological necrosis of tissue resulting from obstruction of the blood supply usually by a thrombus, an embolus, or vascular torsion. "The correlation between IL2 and Troponin I levels indicates that a low expression level of IL2 at 1 h after infarction could be associated with a higher Troponin I level at 24 h." (PMID 30898123, 2019). "For both infarction groups, we found significantly higher levels of interleukin-2 receptor subunit alpha (IL2-RA) and growth/differentiation factor-15 (GDF-15)." (PMID 33396480, 2020).
insomnia (4 papers, 2020 to 2025). A sleep disorder characterized by difficulty in falling asleep and/or remaining asleep. "Our analysis shows that ZSS can effectively act on multiple targets such as TNF and IL-2 simultaneously through various components such as swertisin, jujuboside A, and spinosin, which makes the drug molecules affect the protein, and this achieves the effect of treating insomnia." (PMID 34745308, 2021).
lichen planus (4 papers, 2012 to 2025). A chronic, recurrent, pruritic inflammatory disorder of unknown etiology that affects the skin and mucus membranes. "Thus, the overactivation of cytotoxic CD8+ cells and uninhibited production of proinflammatory cytokines such as IL‐2, TNF‐α, and IFN‐γ by CD4+ T cells play an important role in the implication of Lichen planus." (PMID 40626171, 2025). "The pathophysiologic mechanism might be the Th1 response that is elicited by the vaccines, which in turn leads to the elevation of interleukin‐2 (IL‐2), tumor necrosis factor‐α (TNF‐α), and interferon‐γ (IFN‐γ) levels, and therefore, lichen planus induction." (PMID 35140945, 2022).
liver cirrhosis (4 papers, 2016 to 2024). "The previous studies revealed that increased levels of TNF-α as well as IL-2, IL-6, and IL-10 in serum of patients play important roles in the progress of inflammation of severe hepatitis B-related liver cirrhosis." (PMID 27975051, 2016).
lupus erythematosus (4 papers, 2022 to 2024). An autoimmune, connective tissue chronic inflammatory disorder affecting the skin, joints, kidneys, lungs, heart, and the peripheral blood cells. "Low-dose IL-2 increased the number of Treg, and restored the T follicular regulatory (Tfr)/T follicular helper (Tfh) cell balance in parallel with the reduction of prednisone use and disease activity (Safety of Estrogens in Lupus Erythematosus National Assessment [SELENA]-SLEDAI)." (PMID 39483464, 2024).
medulloblastoma (4 papers, 2002 to 2023). A malignant, invasive embryonal neoplasm arising from the cerebellum. "A phase II clinical trial in patients with recurrent medulloblastoma (NCT00014573) combines chemotherapy with vaccine therapy, stem cell transplantation, and IL-2." (PMID 35565414, 2022). "In pediatric medulloblastoma, it has been revealed that B7-H3 CAR T cells, by producing IFNg, TNFa, and IL-2, can have antitumor effects in xenograft models." (PMID 33673696, 2021). "While pathways involved in cell cycle, and DNA repair were up-regulated in medulloblastoma, NFΚB pathway, RELA pathway, Interleukin-2 (IL2), Interleukin-27(IL27) signaling pathways were down-regulated in medulloblastoma compared to healthy cerebellum samples from GTEx." (PMID 36918656, 2023). "The sensitivity of medulloblastoma cells to cpIL4-PE could be eliminated by concurrent incubation with IL-4 or IL-13, but not with IL-2." (PMID 11870521, 2002).
nephritis (4 papers, 2018 to 2023). Inflammation of renal tissue. "For IL-2 treatment of LN patients, low-dose human IL-2 in treatment of active LN patients improved nephritis, achieved a higher remission rate as compared with placebo, and promoted the proliferation of Treg cells." (PMID 38164134, 2023). "Complementary to these abnormalities we found low frequencies of IL-2 producing cells among intrarenal effector/memory Tcon in mice with active nephritis." (PMID 31614462, 2019). "In the context of SLE, rapamycin ameliorated nephritis and improved IL-2 production in MRL/lpr mice." (PMID 30524430, 2018). "Therefore, (NZB × NZW) F1 mice with active nephritis were treated daily with a subcutaneous injection of recombinant IL-2 (25 ng/g body weight) for 5 consecutive days." (PMID 31614462, 2019). "Although not specifically evaluating nephritis, this trial may provide an overall indication of the efficacy of IL-2 in paediatric IgAV." (PMID 37755547, 2023).
Newcastle disease (4 papers, 2012 to 2024). A condition caused by infection by the Newcastle disease virus, which may be characterized by conjunctivitis, respiratory illness, and diarrhea. "Although productive parameters were not responded to the dietary n-3 PUFA in a dose-dependent manner, spleen weight, IBD and Newcastle disease antibody titers and IL-2 and IFN-γ concentrations were constantly elevated by n-3 PUFA enrichment." (PMID 22273277, 2012). "In vivo results show that GPS-1 combined with Newcastle disease (ND) vaccine had the best efficacy at significantly increasing chickens' body weight and ND serum antibody titer, enhancing their secretion of IL-2 and IFN- γ, and promoting the development of immune organs." (PMID 36090181, 2022). "Newcastle disease and Infectious Bronchitis elicit immune response in chickens after intranasal administration;Inducement of higher titers of IgG and IgA antibodies;Increase the proliferation of lymphocytes and induce higher levels of cytokines, including IL-2, IL-4, and IFN-γ." (PMID 38005381, 2023).
nosocomial infection (4 papers, 2014 to 2024). An infection acquired in a hospital or other healthcare setting. "Stenotrophomonas maltophilia, a pathogen causing hospital-acquired infections, produces cytokines like IL-2, IFN-γ, and TNF-α, triggering systemic inflammation." (PMID 39483762, 2024). "A recent study reported decreased T-cell ex vivo PHA-induced production of IFNγ, IL-2 and IL-10 in children with septic shock that went on to develop persistent or nosocomial infection compared with septic shock children who did not." (PMID 27015534, 2016). "Among septic shock children, those who went on to develop persistent or nosocomial infection had decreased T-cell ex vivo PHA-induced production of IFN-γ (P = 0.01), IL-2 (P = 0.01), IL-4 (P = 0.008), and IL-10 (P = 0.001) compared with septic shock children who did not." (PMID 25005517, 2014).
pemphigus (4 papers, 2008 to 2024). Pemphigus is a group of rare autoimmune diseases that cause blistering of the skin and mucous membranes (mouth, nose, throat, eyes, and genitals).This conditioncan occur at any age, but often strikes people in middle or older age. "IL-2 is one of the main activators of T lymphocytes.Increased values of soluble receptor for IL-2 (sIL-2R) were detected in sera ofpatients with pemphigus, and these values correlated with activity of thedisease." (PMID 18584045, 2008). "One systematic review of cytokine research in pemphigus revealed elevated levels of TNF-α, TGF-β, interleukin (IL)-8, IL-10, IL-12, IL-17, and IL-21, along with reduced levels of IL-2 and IL-23." (PMID 39463588, 2024).